DLGAP4 (DLG associated protein 4)
Description:
May play a role in the molecular organization of synapses and neuronal cell signaling. Could be an adapter protein linking ion channel to the subsynaptic cytoskeleton. May induce enrichment of PSD-95/SAP90 at the plasma membrane.
Synonyms: DAP-4; SAPAP-4; DAP4; KIAA0964; SAPAP4; DLP4
Tractability: Antibody: its Gene Ontology location is reachable by antibodies, with high confidence; UniProt places it where antibodies can reach, with medium confidence. PROTAC: its protein half-life has been measured.
Gene: Protein-coding gene on chromosome 20 (36,306,302 to 36,528,637, forward strand). Ensembl gene ENSG00000080845.
Subcellular location: Membrane
Subcellular location (Human Protein Atlas): Nucleoplasm; Focal adhesion sites; Vesicles
Pathways (Reactome):
Neuronal System: Neurexins and neuroligins
Gene Ontology:
Molecular function: protein binding; molecular adaptor activity
Biological process: modulation of chemical synaptic transmission; modification of postsynaptic structure; regulation of synapse maturation; signaling
Cellular component: glutamatergic synapse; plasma membrane; postsynaptic specialization; cholinergic synapse; membrane; neuromuscular junction; synapse
Genetic constraint (gnomAD): Loss-of-function variants: 18 observed, 80.62 expected, observed/expected ratio (o/e) 0.22, 90% interval 0.15 to 0.33. The upper end of that interval is the gene's LOEUF score, 0.33, which puts it in group 1 of 6, group 1 being the genes least tolerant of losing a copy. Missense variants: 1,085 observed, 1,360.1 expected, observed/expected ratio (o/e) 0.8, 90% interval 0.76 to 0.84. Synonymous variants: 547 observed, 576.13 expected, observed/expected ratio (o/e) 0.95, 90% interval 0.88 to 1.02.
Homologues: Orthologues: chimpanzee DLGAP4 (99% identical), dog DLGAP4 (98% identical), guinea pig DLGAP4 (97% identical), mouse Dlgap4 (97% identical), macaque DLGAP4 (97% identical), rat Dlgap4 (96% identical), pig DLGAP4 (95% identical), tropical clawed frog dlgap4 (62% identical), zebrafish dlgap4b (52% identical), zebrafish dlgap4a (17% identical). Paralogues in human: DLGAP1 (48% identical), DLGAP2 (43% identical), DLGAP3 (37% identical), DLGAP5 (14% identical).
Diseases named in the same sentence as DLGAP4 in open-access papers:
DLGAP4 is named in the same sentence as 34 diseases in open-access papers, as found by Europe PMC text mining. Sharing a sentence is not in itself a finding about the gene and the disease. The quoted sentences say what the papers report.
cerebellar ataxia (4 papers, 2017 to 2020). A neurological syndrome characterized by clumsy and uncoordinated movement of the limbs, trunk, and cranial muscles. "DLGAP4 is involved in the transmission of neuronal signals and has not been excavated for its role in tumors, but its epigenetic changes and dysfunction have been found to be related to early-onset cerebellar ataxia." (PMID 32547879, 2020). "The fourth DLGAP gene, DLGAP4, has been related to cerebellar ataxia." (PMID 28870203, 2017). "Given the apparent intolerance of DLGAP4 to heterozygous LoF mutations it seems likely that the mild ataxia does not result from DLGAP4 haploinsufficiency, but is due to an increased monoallelic expression of specific SAPAP4 mRNAs from the locus located on der866." (PMID 30664629, 2019). "It was previously shown that such epigenetic regulation could alter the gene expression of DLGAP4 in cerebellar Purkinje cells, causing early-onset non-progressive cerebellar ataxia, and bipolar disorder in humans." (PMID 31783652, 2019). "DLGAP4 is proposed as a candidate gene for cerebellar ataxia but DLGAP4 was never investigated in studies of the Stargazer mouse, a mouse model of cerebellar ataxia." (PMID 28870203, 2017).
Anxiety (3 papers, 2019 to 2023). Intense feelings of nervousness, tension, or panic often arise in response to interpersonal stresses. "There was an association between anxiety levels (HADS-A scores) and genes involved in the activity of excitatory neurotransmitters: PTPRN2 (rs3857647), DLGAP4 (rs8114927), and STK24 (rs9517326)." (PMID 38328521, 2023). "Behavioural analysis of all mice that completed the whole 5 min EPM test phase (n = 6 Dlgap4geo/geo and 11 Dlgap4+/+ males) revealed a high preference of Dlgap4geo/geo animals for exploring open versus closed arms, indicative of a decrease in anxiety." (PMID 30664629, 2019). "Notably, many of the discovered variants, including one DLGAP4 variant and PTPRD (rs832264) on chromosome 9, were associated with lower HADS-A scores, i.e., with the absence of clinical anxiety symptoms." (PMID 38328521, 2023).
ischemic stroke (3 papers, 2020 to 2025). A stroke disorder caused by obstruction of blood flow to the brain, due to thrombotic (local blood clot formation) or embolic (due to a blood clot or other material traveling from another site) event. "In the realm of ischemic stroke, circular RNA DLGAP4 has been identified for its role in ameliorating the condition by regulating endothelial-mesenchymal transition linked to blood–brain barrier integrity." (PMID 41262976, 2025). "While circRNA DLGAP4, originated from exons 8, 9 and 10 of fourth DLGAP (DLGAP4) gene, negatively associated with ischemic stroke development and severity, probably through influencing blood–brain barrier integrity or inflammation process." (PMID 37186176, 2023). "Many experiments have explored the functions of the circRNAs reported in this study, among which circRNA HECTD1 and circRNA DLGAP4 were the mostly researched in relation to ischemic stroke." (PMID 37186176, 2023). "In addition, circ-DLGAP4 can inhibit ischemic stroke outcomes via sponging miR-143 to modulate blood–brain barrier integrity." (PMID 33230102, 2020).
Stroke (3 papers, 2020 to 2024). Sudden impairment of blood flow to a part of the brain due to occlusion or rupture of an artery to the brain. "A previous study also shows that the circular RNA DLGAP4 improves stroke outcome by acting as a miR-143 sponge." (PMID 39000490, 2024). "In stroke models, circ‐DLGAP4 sponges the pro‐inflammatory gene miR‐143, suggesting the involvement of circ‐DLGAP4 in inflammatory response." (PMID 32452125, 2020). "Interestingly, overexpression of circRNA DLGAP4 ameliorates neurological deficit and infarct volume after transient focal ischemia in a stroke mouse model." (PMID 32175077, 2020).
autism (2 papers, 2020 to 2025). Persistent deficits in social interaction and communication and interaction as well as a markedly restricted repertoire of activity and interest as well as repetitive patterns of behavior.
diabetic kidney disease (2 papers, 2020 to 2023). Progressive kidney disorder caused by vascular damage to the glomerular capillaries, in patients with diabetes mellitus. "CircRNA DLGAP4 was also reported to have protective effects in diabetic kidney disease progression, myocardial ischemia–reperfusion injury, and Parkinson's disease, all by regulating the most probable target, miR‐143, but different downstream target genes." (PMID 37186176, 2023). "Circ_DLGAP4 induced diabetic nephropathy progression by activating ERBB3." (PMID 33230102, 2020).
gastric cancer (1 paper, 2022). A primary or metastatic malignant neoplasm involving the stomach. "They found that the expression of DLGAP4 in gastric cancer tissue was significantly higher than that in normal gastric tissue." (PMID 36396671, 2022). "There is a clear correlation between high expression of DLGAP4 and a poor prognosis for gastric cancer patients, indicating that it can be used as a potential prognostic marker." (PMID 36396671, 2022). "Although Liu's37 bioinformatics analysis showed that DLGAP4 may play an oncogenic role in gastric cancer and may become a prognostic indicator for predicting gastric cancer, it has not been verified in in vivo and in vitro functional experiments." (PMID 36396671, 2022).
glaucoma (1 paper, 2023). Increased pressure in the eyeball due to obstruction of the outflow of aqueous humor. "We found that upstream stimulators of Aurora proliferative signaling had increased expression in UON after three days in the glaucoma model (e.g., Cenpa, Arhgef, Dlgap4)." (PMID 37762022, 2023).
hepatocellular carcinoma (1 paper, 2022). A malignant tumor that arises from hepatocytes. "Disc large associated protein 4 (DLGAP4) plays an important role in neurological diseases, but the role and mechanism of DLGAP4 in hepatocellular carcinoma (HCC) remain unclear." (PMID 36396671, 2022).
heterotopia (1 paper, 2022). "In this study we identify a new gene for subependymal and subcortical heterotopia, revealing a de novo Disks large-associated protein 4 (DLGAP4) frameshift variation in a patient with unilateral heterotopia and polymicrogyria, resembling the EML1 phenotype." (PMID 35585091, 2022).
renal fibrosis (1 paper, 2025). A final common manifestation of a wide variety of chronic kidney diseases characterized by glomerulosclerosis and tubulointerstitial fibrosis. "For example, decreased CircRNA_010383 increases proteinuria and renal fibrosis, while elevated Circ_0125310 and Circ_DLGAP4 promote mesangial cell proliferation and fibrosis." (PMID 39941397, 2025).
cancer (5 papers, 2018 to 2024). A tumor composed of atypical neoplastic, often pleomorphic cells that invade other tissues. "Liu37 and others believed that DLGAP4 may have similar cancer-promoting functions as DLGAP5." (PMID 36396671, 2022). "However, the role of DLGAP4 in cancer has rarely been studied." (PMID 36396671, 2022). "In addition, the PPARβ/δ signalling pathway may mediate the cancer-promoting effect of DLGAP4 in HCC." (PMID 36396671, 2022).
tumor (3 papers, 2022 to 2024). "We further verified the expression difference of DLGAP4 between tumour tissues and normal tissues in HCC patients at the protein level based on the HPA database." (PMID 36396671, 2022). "Therefore, DLGAP4 may play a tumour-promoting role in HCC patients." (PMID 36396671, 2022). "The results showed that the prediction of prognosis based on DLGAP4 expression level was better than that based on traditional methods, such as AFP, pathological stage, T stage, M stage, tumour status, residual tumour, age, and sex." (PMID 36396671, 2022).
DLGAP4 also shares sentences with these, for which no sentence is quoted: infection (3 papers); bipolar disorder (2); Cognitive impairment (2); abscess (1); Ataxia (1); brain disease (1); Cerebral ischemia (1); Chudley-McCullough syndrome (1); fragile X syndrome (1); Hepatic steatosis (1); lung carcinoma (1); myocardial ischemia (1); neurodevelopmental disorder (1); neurological diseases (1); Parkinson disease (1); polymicrogyria (1); Sepsis (1); skin abscess (1); staphylococcal infection (1); steatosis (1); type 2 diabetes (1).